SCN3B (sodium voltage-gated channel beta subunit 3)
Description:
Regulatory subunit of multiple voltage-gated sodium (Nav) channels directly mediating the depolarization of excitable membranes. Navs, also called VGSCs (voltage-gated sodium channels) or VDSCs (voltage-dependent sodium channels), operate by switching between closed and open conformations depending on the voltage difference across the membrane. In the open conformation they allow Na(+) ions to selectively pass through the pore, along their electrochemical gradient. The influx of Na+ ions provokes membrane depolarization, initiating the propagation of electrical signals throughout cells and tissues. The accessory beta subunits participate in localization and functional modulation of the Nav channels. Modulates the activity of SCN2A/Nav1.2, causing a hyperpolarizing shift in the voltage-dependence of inactivation of the channel and increasing the fraction of channels operating in the fast gating mode (By similarity). Modulates the activity of SCN5A/Nav1.5. Could also regulate the atypical sodium channel SCN7A/Nav2.1. Modulates the activity of SCN10A/Nav1.8, regulating its oligomerization and accelerating the recovery from inactivation.
Synonyms: HSA243396; SCNB3; ATFB16; BRGDA7
Tractability: Small molecule: a structure with a bound ligand is known. Antibody: UniProt places it where antibodies can reach, with high confidence; its Gene Ontology location is reachable by antibodies, with high confidence; UniProt predicts a signal peptide or a membrane-spanning region. PROTAC: its protein half-life has been measured.
Safety:
Unwanted effects reported when the protein is acted on. In parentheses: how it was acted on, where the effect was seen, and who reports it.
agitation (inhibition, acute dosing; nervous system, respiratory, cardiovascular; source: Lynch et al. (2017))
cardiac arrhythmia (inhibition, acute dosing and activation, acute dosing; nervous system, respiratory, cardiovascular; source: Lynch et al. (2017))
coma (inhibition, acute dosing; nervous system, respiratory, cardiovascular; source: Lynch et al. (2017))
convulsions (activation, acute dosing; nervous system, respiratory, cardiovascular; source: Lynch et al. (2017))
decreased blood pressure (inhibition, acute dosing; nervous system, respiratory, cardiovascular; source: Lynch et al. (2017))
decreased cardiac conduction (inhibition, acute dosing; nervous system, respiratory, cardiovascular; source: Lynch et al. (2017))
decreased cardiac contractility (inhibition, acute dosing; nervous system, respiratory, cardiovascular; source: Lynch et al. (2017))
decreased gastrointestinal transit (inhibition, acute dosing; nervous system, respiratory, cardiovascular; source: Lynch et al. (2017))
decreased locomotor activity (activation, acute dosing; nervous system, respiratory, cardiovascular; source: Lynch et al. (2017))
decreased pain (inhibition, acute dosing; nervous system, respiratory, cardiovascular; source: Lynch et al. (2017))
decreased respiratory rate (inhibition, acute dosing; nervous system, respiratory, cardiovascular; source: Lynch et al. (2017))
decreased sweating (inhibition, acute dosing; nervous system, respiratory, cardiovascular; source: Lynch et al. (2017))
decreased urine excretion (inhibition, acute dosing; nervous system, respiratory, cardiovascular; source: Lynch et al. (2017))
decreased/increased convulsions (inhibition, acute dosing; nervous system, respiratory, cardiovascular; source: Lynch et al. (2017))
decreased/increased heart rate (inhibition, acute dosing; nervous system, respiratory, cardiovascular; source: Lynch et al. (2017))
dyspnea (activation, acute dosing; nervous system, respiratory, cardiovascular; source: Lynch et al. (2017))
increased heart rate (activation, acute dosing; nervous system, respiratory, cardiovascular; source: Lynch et al. (2017))
increased pupil diameter (inhibition, acute dosing; nervous system, respiratory, cardiovascular; source: Lynch et al. (2017))
increased QRS complex (inhibition, acute dosing; nervous system, respiratory, cardiovascular; source: Lynch et al. (2017))
Gene: Protein-coding gene on chromosome 11 (123,629,187 to 123,655,244, reverse strand). Ensembl gene ENSG00000166257.
Subcellular location: Cell membrane
Subcellular location (Human Protein Atlas): Cytosol; Plasma membrane; Vesicles
Pathways (Reactome):
Developmental Biology: Interaction between L1 and Ankyrins
Muscle contraction: Phase 0 - rapid depolarisation
Gene Ontology:
Molecular function: protein binding; sodium channel regulator activity; transmembrane transporter binding; sodium channel inhibitor activity; voltage-gated sodium channel activity involved in cardiac muscle cell action potential
Biological process: atrial cardiac muscle cell action potential; cardiac muscle cell action potential involved in contraction; cardiac muscle contraction; membrane depolarization; membrane depolarization during action potential; membrane depolarization during cardiac muscle cell action potential; positive regulation of sodium ion transport; protein localization to plasma membrane; regulation of atrial cardiac muscle cell membrane depolarization; regulation of heart rate by cardiac conduction; regulation of ventricular cardiac muscle cell membrane depolarization; sodium ion transmembrane transport; ventricular cardiac muscle cell action potential; positive regulation of heart rate; regulation of membrane potential; SA node cell action potential; sodium ion transport; nervous system development
Cellular component: plasma membrane; voltage-gated sodium channel complex; cation channel complex; membrane; Z disc
Genetic constraint (gnomAD): Loss-of-function variants: 11 observed, 26.89 expected, observed/expected ratio (o/e) 0.41, 90% interval 0.26 to 0.68. The upper end of that interval is the gene's LOEUF score, 0.68, which puts it in group 2 of 6, group 1 being the genes least tolerant of losing a copy. Missense variants: 218 observed, 292.9 expected, observed/expected ratio (o/e) 0.74, 90% interval 0.67 to 0.83. Synonymous variants: 109 observed, 115.97 expected, observed/expected ratio (o/e) 0.94, 90% interval 0.8 to 1.1.
Gene-disease validity (ClinGen):
ClinGen rates the evidence that SCN3B causes each of these diseases.
atrial fibrillation (autosomal dominant): Disputed. A disorder characterized by an electrocardiographic finding of a supraventricular arrhythmia characterized by the replacement of consistent P waves by rapid oscillations or fibrillatory waves that vary in size, shape and timing and are accompanied by an irregular ventricular response.
Brugada syndrome (autosomal dominant): Refuted. A genetically heterogeneous condition characterized by complete or incomplete right bundle branch block accompanied by ST elevation in leads V1-V3.
Homologues: Orthologues: chimpanzee SCN3B (100% identical), rat Scn3b (98% identical), guinea pig SCN3B (98% identical), mouse Scn3b (98% identical), dog SCN3B (97% identical), pig SCN3B (97% identical), rabbit SCN3B (97% identical), macaque SCN3B (91% identical), tropical clawed frog scn3b (66% identical), zebrafish scn3b (52% identical). Paralogues in human: SCN1B (47% identical).
Diseases named in the same sentence as SCN3B in open-access papers:
SCN3B is named in the same sentence as 37 diseases in open-access papers, as found by Europe PMC text mining. Sharing a sentence is not in itself a finding about the gene and the disease. The quoted sentences say what the papers report.
Brugada syndrome (8 papers, 2016 to 2024). "Other genes, such as SCN1B, SCN2B, SCN3B, and GPD1L, contribute to reduced INa and Brugada syndrome, with various clinical phenotypes associated with these mutations." (PMID 39583597, 2024).
cardiac arrhythmia (8 papers, 2014 to 2025). Any disturbances of the normal rhythmic beating of the heart or MYOCARDIAL CONTRACTION. "Multiple SCN1B and SCN3B mutations are associated with cardiac arrhythmia." (PMID 34867379, 2021). "Several inherited cardiac arrhythmias are associated with point mutations in the human SCN3B gene." (PMID 24567321, 2014). "In mice, deletion of the β3 subunit gene (Scn3b) is associated with cardiac arrhythmias." (PMID 24567321, 2014). "Considering the commonplace of arrhythmia events in patients treated with doxorubicin, it is biologically plausible to attach importance to the crucial role of Scn3b in AIC." (PMID 34732131, 2021). "People with mutations in the β3 subunit (SCN3B gene) show cardiac conduction problems and in mice deletion of SCN3B leads to cardiac arrhythmias." (PMID 32266288, 2020). "Although the role of Scn3b in AIC has not been reported ever, the increased expression of Scn3b modulated by interleukin 2 was found to be associated with arrhythmia." (PMID 34732131, 2021). "In present study, we observed that high expression level of the SCN3B which induced by IL-2 can increase the sodium current density, these results suggested that increased serum level of IL-2 can affect various cardiac arrhythmias by its effect on the SCN3B and sodium current density." (PMID 26728597, 2016). "In conclusion, the present study suggested that IL-2, a pro-inflammatory cytokine, may play role in the arrhythmia by its affection on SCN3B and sodium current density." (PMID 26728597, 2016).
epilepsy (6 papers, 2013 to 2025). A brain disorder characterized by episodes of abnormally increased neuronal discharge resulting in transient episodes of sensory or motor neurological dysfunction, or psychic dysfunction. "This study investigated several genetic variants of SCN genes (SCN1A, SCN2A, SCN3A, SCN1B, SCN2B, SCN3B and SCN8A) and their association with epilepsy risk; these genes have been studied in this regard and conflicted results were reported." (PMID 35801810, 2022). "SCN2A, SCN3A, and SCN3B were upregulated in neurons, described to be involved in neuronal excitation and epilepsy pathogenesis." (PMID 23690787, 2013). "Therefore, we speculated that SCN3B might play an important role in the progression of epilepsy through sodium channels." (PMID 26742644, 2016). "The dysregulation of C1QB, C1S, CFI, SCN3B and FN1 may be used potential gene targets for epilepsy treatment." (PMID 26742644, 2016). "Furthermore, genes such as SCN3B, EPHA4, GABRB3, and SCN2A may play roles in the development of epilepsy in the context of AD." (PMID 38999445, 2024). "Additionally, C1QB, C1S, CFI, SCN3B and FN1 may be potential therapeutic targets for epilepsy." (PMID 26742644, 2016).
atrial fibrillation (5 papers, 2017 to 2025). "These included channel subunits previously linked to atrial fibrillation, including SCN3B and SCN4B41, which were more highly expressed in the LA, and KCNJ5 and HCN441, which were more highly expressed in the RA." (PMID 30224797, 2018). "Interestingly and closely related with our results, IL-2 was able to induce in vitro the expression of SCN3B and sodium current density, increasing of atrial action potential duration and IL-2 has been linked to prognosis for atrial fibrillation in patients." (PMID 28327099, 2017). "Some previous studies have established that genetic modification in sodium voltage-channel genes encoding for the cardiac β-subunits, such as SCN1B, SCN2B, SCN3B and SCN4B, can result in atrial fibrillation (AF)." (PMID 36362949, 2022).
glioma (5 papers, 2025). A benign or malignant brain and spinal cord tumor that arises from glial cells (astrocytes, oligodendrocytes, ependymal cells). "Similarly, voltage-gated sodium channel β3 subunit (SCN3B) has been identified as a prognostic biomarker for gliomas, specifically oligodendroglioma, where higher levels of SCN3B correlate with longer survival." (PMID 40361384, 2025). "For example, discovering the role of single gene in a single tumor, they argued in detail the identity of SCN3B and CDK2 in glioma, and proved the role of AIMP1, CNIH4 in head and neck squamous cell carcinoma." (PMID 40108724, 2025). "While TCGA has revolutionized cancer biomarker discovery, exemplified by studies identifying SCN3B in glioma, CDK2 in glioma prognosis, AIMP1/CNIH4 in head-neck squamous carcinoma, and RAD50 in breast cancer, its limitations must be acknowledged." (PMID 40860678, 2025). "Studies such as those on SCN3B in glioma, CDK2 in glioma, AIMP1 in head-neck squamous cell carcinoma and CNIH4 in head and neck squamous cell carcinoma demonstrate the diverse applications of TCGA data in cancer research." (PMID 40290723, 2025).
Alzheimer disease (2 papers, 2019 to 2022). A progressive, neurodegenerative disease characterized by loss of function and death of nerve cells in several areas of the brain leading to loss of cognitive function such as memory and language. "Pathological levels (both increase and decrease) of SCN3B mRNA have been implicated in multiple neurodegenerative diseases such as amyotrophic lateral sclerosis and Alzheimer’s disease as well as cancer." (PMID 35309145, 2022). "These genes were selected for their involvement in cognitive functioning since SCN3B and HOPX were lower expressed and DSP was higher expressed in hippocampal region of patients with Alzheimer’s disease." (PMID 31610812, 2019).
Ventricular arrhythmia (2 papers, 2008 to 2021). "The NaV β-subunits play a critical role in the regulation of cardiac NaV channel function, as demonstrated in SCN1B- and SCN3B-null mice whose ventricular cardiomyocytes exhibit abnormal electrophysiology and propensity to ventricular arrhythmias." (PMID 34867379, 2021). "In contrast, under such circumstances, a significant proportion of Scn3b−/− hearts showed ventricular arrhythmias." (PMID 19351516, 2008).
Anxiety (1 paper, 2008). Intense feelings of nervousness, tension, or panic often arise in response to interpersonal stresses. "Additionally, vision, locomotor activity and anxiety tests showed similar results in both WT and Scn3b−/− mice." (PMID 19351516, 2008).
cervical cancer (1 paper, 2018). A primary or metastatic malignant neoplasm involving the cervix. "In cervical cancer tissues, SCN3B mRNA level is increased, whereas SCN1B, SCN2B and SCN4B mRNA levels are decreased." (PMID 29723302, 2018).
Cognitive impairment (1 paper, 2022). Abnormal cognition is characterized by deficits in thinking, reasoning, or remembering. "In the present study, beta-sitosterol, an active ingredient in the Shunaoxin pill, was shown to bind stably to SCN3B, thus possibly playing a role in the development of diabetes-induced cognitive impairment." (PMID 36341127, 2022). "Active ingredients of the Shunaoxin pill may alleviate cognitive impairment in diabetic patients by targeting the proteins OPRK1, GABRA5, GABRP, and SCN3B." (PMID 36341127, 2022).
diabetic neuropathy (1 paper, 2025). A chronic, pathological complication associated with diabetes mellitus, where nerve damages are incurred due to diabetic microvascular injury involving small blood vessels that supply these nerves, resulting in peripheral and/or autonomic nerve dysfunction. "Scn3b is upregulated in nerve injuries and streptozotocin models of painful diabetic neuropathy, all of which are associated with expression of Atf3 in sensory neurons." (PMID 41322115, 2025).
idiopathic ventricular fibrillation (1 paper, 2016). "Mutations in SCN3B have been identified in idiopathic ventricular fibrillation, including BrS." (PMID 27677334, 2016).
neuropathy (1 paper, 2022). A disorder affecting the nervous system that manifests with pain, tingling, numbness, and/or muscle weakness. "The higher the temperature was, the higher the expression of SCN3B protein was, which also indicated neuropathy damage." (PMID 35436702, 2022). "Therefore, the authors hypothesize if the expression of SCN9A and SCN3B protein is downregulated, it could inhibit the neuropathy response, such as nerve injury and nerve pain." (PMID 35436702, 2022).
cancer (9 papers, 2015 to 2025). A tumor composed of atypical neoplastic, often pleomorphic cells that invade other tissues. "Further studies are needed to fully understand the potential role of SCN3B as well as the mechanism involved in the pro-apoptotic effect in cancer cells." (PMID 33817575, 2021). "In line with this interpretation, SCN3B expression was increased almost 2-fold in CeCa biopsies when compared with non-cancer samples." (PMID 33817575, 2021). "In contrast, SCN3B expression was increased in cervical cancer biopsies when compared to non-cancer samples." (PMID 26283962, 2015). "In non-tumour breast samples, SCN3B expression was the lowest among all NaVβ encoding genes and was still significantly reduced in cancer samples." (PMID 33817575, 2021). "Both metrics were analyzed, but AUC remains the gold standard for direct comparison with prior radiomics studies, such as those investigating RAD51, SCN3B, and CDK2 in cancer biomarker discovery." (PMID 40535132, 2025). "No studies to date have investigated the potential connections between these gene-cancer pairs, therefore, SCN3A-LGG, SCN3B-LGG, SCN4A-KIRC, and SCN1B-PAAD would be potential clinically significant research topics for future study." (PMID 39060933, 2024). "Among these gene-cancer pairs, SCN3A-LGG, SCN3B-LGG, SCN4A-KIRC, SCN1B-UVM, and SCN1B-PAAD have a relatively high gene expression level, and have a relatively large case number except for UVM (n = 79)." (PMID 39060933, 2024). "Expressions of SCN1B, SCN2B and SCN3B were lower in cancer compared with non-cancer tissues." (PMID 27917859, 2016).
tumor (5 papers, 2022 to 2025). "By combining these gene sets, we identified the leading genes that were associated with the tumor laterality: CACNA1C, CACNA2D2, CACNB2, KCNJ11, SCN3A, and SCN3B, signature that we called: 6-ICH signature." (PMID 37446299, 2023).
neurodevelopmental disorder (2 papers, 2018 to 2025). A behavioral and cognitive disorder with onset during the developmental period that involves impaired or aberrant development of intellectual, motor, or social functions. "Although SCN3B has been associated with cardiac disorders, a link with neurodevelopmental disorders (NDD) has not been established." (PMID 40879121, 2025).
SCN3B also shares sentences with these, for which no sentence is quoted: Arrhythmia (3 papers); ventricular fibrillation (3); breast carcinoma (2); cardiomyopathy (2); head and neck squamous cell carcinoma (2); neurodegenerative disease (2); amyotrophic lateral sclerosis (1); Ataxia (1); autism (1); Cardiac disease (1); channelopathies (1); congenital myasthenic syndrome (1); dementia (1); diabetes (1); Intellectual disability (1); long QT syndrome (1); metastatic colorectal cancer (1); myocardial ischemia (1); oligodendroglioma (1); ventricular tachycardia (1); viral myocarditis (1).